ADM (adrenomedullin)
Diseases named in the same sentence as ADM in open-access papers (continued):
Sharing a sentence is not in itself a finding about the gene and the disease.
ischemic stroke (5 papers, 2018 to 2023). A stroke disorder caused by obstruction of blood flow to the brain, due to thrombotic (local blood clot formation) or embolic (due to a blood clot or other material traveling from another site) event. "Higher levels of leptin, IL1ra, and adrenomedullin were associated with increased ischemic stroke risk." (PMID 36691017, 2023). "In addition, a compelling study showed that elevated ADM levels were significantly associated with the severity of neurological damage, higher mortality, and poorer outcomes in patients with ischaemic stroke." (PMID 35962388, 2022). "Bio-ADM levels significantly increased in patients with ischemic stroke who died compared to surviving patients (40.4 pg/ml vs. 23.8 pg/ml, p < 0.001) or in those with composite outcomes compared to those with no events (36.9 pg/ml vs. 23.5 pg/ml, p < 0.001)." (PMID 36964268, 2023). "Third, more in vivo and in vitro studies are needed to clarify the underlying mechanism of these correlations among ADM, ANXA3, SLC22A4 and VIM and infiltrated immune cells in ischaemic stroke." (PMID 35962388, 2022). "In summary, we determined that ADM, ANXA3, SLC22A4 and VIM are diagnostic markers of ischaemic stroke." (PMID 35962388, 2022). "The high expression of ADM in the samples analyzed led us to hypothesize that adrenomedullin was secreted in the brain of the affected subjects and is still secreted years after the ischemic stroke." (PMID 37508918, 2023). "The mechanism underlying the relationship between ADM, ANXA3, SLC22A4 and VIM and immune cells may be of great significance for the pathogenesis and progression of ischaemic stroke, and related research of these genes could provide new therapeutic insight for ischaemic stroke." (PMID 35962388, 2022). "The ROC analyses based on the training set, validation set, and our clinical samples showed that the ADM, ANXA3, SLC22A4 and VIM genes remained highly effective in distinguishing the ischaemic stroke patients from the normal subjects." (PMID 35962388, 2022). "Eight hub genes (ADM, ANXA3, CARD6, CPQ, SLC22A4, UBE2S, VIM and ZFP36) were revealed to be significantly correlated with ischaemic stroke by the LASSO logistic regression and SVM-RFE algorithm." (PMID 35962388, 2022). "Eight hub genes (ADM, ANXA3, CARD6, CPQ, SLC22A4, UBE2S, VIM and ZFP36) were revealed to be significantly correlated with ischaemic stroke by a LASSO logistic regression and SVM-RFE machine learning methods." (PMID 35962388, 2022). "The expression levels of the ADM, ANXA3, CARD6, CPQ, SLC22A4 and VIM genes were significantly increased in the ischaemic stroke patients compared with those in the healthy subjects (p < 0.05–0.01)." (PMID 35962388, 2022). "Further verifying the expression levels of these key genes in ischaemic stroke patients, we noticed that the expression levels of ADM, ANXA3, SLC22A4 and VIM were significantly increased in the ischaemic stroke patients compared with those in the normal subjects (p < 0.01)." (PMID 35962388, 2022). "Therefore, further studies are needed to explore whether therapies targeting these genes such as ADM, ANXA3, SLC22A4 and VIM will bring some similar risks to patients with ischaemic stroke." (PMID 35962388, 2022).
Anxiety (4 papers, 2012 to 2025). Intense feelings of nervousness, tension, or panic often arise in response to interpersonal stresses. "As expected, we found significantly greater reductions in plasma ADM levels, anxiety, and sleep problems in both intervention groups compared to the control group." (PMID 30020987, 2018). "Congruently, there was a significant relationship between changes in ADM and changes in anxiety, in line with the result of one previous study." (PMID 30020987, 2018). "Compared to the control group, we observed significantly greater pre-post reductions in plasma ADM levels (p < .001), anxiety (p ≤ .002), and sleep problems (p ≤ .003) in both intervention groups." (PMID 30020987, 2018). "Altered expression of ADM has been previously correlated with mood disorders, while its knockout in mice leads to heightened anxiety-like behavior." (PMID 23087602, 2012).
atrial fibrillation (4 papers, 2018 to 2024). A disorder characterized by an electrocardiographic finding of a supraventricular arrhythmia characterized by the replacement of consistent P waves by rapid oscillations or fibrillatory waves that vary in size, shape and timing and are accompanied by an irregular ventricular response. "Elevated bio-ADM levels are associated with catecholamine therapy, postoperative atrial fibrillation, and mortality." (PMID 38834580, 2024).
cardiac ischemia (4 papers, 2021 to 2024). "In the myocardial ischemia model, ADM deficiency increased the mortality rate whereas exogenous ADM limited infarct development in mice, perhaps by augmenting the phosphorylation of eNOS and Akt proteins." (PMID 36362188, 2022). "Because of the stability of ADM in whole blood, serum, or plasma, numerous studies have speculated that serum ADM levels can be used as an early warning indicator of cardiac ischemia." (PMID 35355972, 2022).
chronic obstructive pulmonary disease (4 papers, 2019 to 2024). A chronic and progressive lung disorder characterized by the loss of elasticity of the bronchial tree and the air sacs, destruction of the air sacs wall, thickening of the bronchial wall, and mucous accumulation in the bronchial tree. "In a cohort study of 385 patients, elevated levels of ADM, AVP, and ANP were all associated with increased risk of death in patients with stable chronic obstructive pulmonary disease (COPD)." (PMID 31022834, 2019). "It was recently reported that the expression of plasma adrenomedullin increases in chronic obstructive pulmonary disease (COPD), which may reflect the severity of disease and serve as an independent predictor of prognosis." (PMID 35720354, 2022). "In our cohort, bio-ADM levels were significantly associated with the onset of POAF as soon as 12 h postoperatively, as the biomarker identified the patients at risk for inflammatory events, which may subsequently contribute to cardiac arrhythmia." (PMID 38834580, 2024).
gestational diabetes (4 papers, 2022 to 2023). Carbohydrate intolerance first diagnosed during pregnancy. "Therefore, the present study was designed to determine if OMAT and SCAT differentially express proinflammatory and lipid metabolic adipokines, including ADM system, and if so, whether the site-specific differences in their expressions have implications on lipid homeostasis in gestational diabetes." (PMID 35390031, 2022). "Moreover, plasma ADM concentrations are higher in pregnant women with gestational diabetes mellitus (GDM), and ADM inhibits β-cell insulin production and secretion in vitro." (PMID 36180668, 2023).
Headache (4 papers, 2022 to 2024). Cephalgia, or pain sensed in various parts of the head, not confined to the area of distribution of any nerve. "Finally, adrenomedullin was associated with headache induction in other human studies designed to explore the vascular effects of adrenomedullin." (PMID 37370051, 2023).
kidney damage (4 papers, 2010 to 2024). "On the other hand, increased ADM can be associated with reduced renal clearance of this protein in the development of nephropathy, even though it is metabolized in the pulmonary circulation." (PMID 24347823, 2013). "Mmp2 has also been found to cleave adrenomedullin, resulting in production of a vasoconstrictor peptide, and this may be an underlying mechanism that leads to kidney damage." (PMID 26673451, 2015). "Taken together, the elevation of plasma adrenomedullin level in type 1 diabetes(especially in the presence of nephropathy) could participate in the mechanism against progression of vascular damage." (PMID 20181139, 2010). "Elevated levels of adrenomedullin have been suggested to play a compensatory role in CKD, helping to mitigate the progression of kidney damage." (PMID 39200990, 2024).
leiomyoma (4 papers, 2021 to 2024). A well-circumscribed benign smooth muscle neoplasm characterized by the presence of spindle cells with cigar-shaped nuclei, interlacing fascicles, and a whorled pattern. "Endometrial expression of vascular endothelial growth factor (VEGF) and adrenomedullin was increased in patients with fibroids." (PMID 37108180, 2023). "During development of leiomyoma, the pre-existing blood vessels undergo regression and new vessels invade the tumor from the periphery probably promoted by growth factors secreted by the tumor (i.e., basic fibroblast growth factor (bFGF) and adrenomedullin (ADM))." (PMID 34942951, 2021).
myeloma (4 papers, 2017 to 2025). "Adrenomedullin (AM) is a multifunctional peptide which under basal conditions mainly regulates vasodilation and maintains vascular integrity but is also implicated in the pathogenesis of several malignancies, including multiple myeloma (MM)." (PMID 39315734, 2024). "In this context, 2 key myeloma markers, MYC and DKK1, as well as many other cancer-associated genes, including ADM, HDGF, IL15, HGF, STMN1, CDKN1B and CD82, were potentially regulated by the predicted ligands." (PMID 41056512, 2025). "It has been shown that adrenomedullin is expressed by human myeloma cell lines and that it enhances MM‐driven angiogenesis." (PMID 39315734, 2024). "In this study, we found SEs driving known oncogenes (ST3GAL6 and ADM) as w critical subtype-specific drivers (MAF and NUAK1) in myeloma pathogenesis." (PMID 33579893, 2021). "It has also been shown that adrenomedullin is expressed in a hypoxia‐dependent and hypoxia‐independent manner by L363, LME‐1 and RPMI8226 human myeloma cell lines and that it enhances MM‐driven angiogenesis mainly by stimulating endothelial cell proliferation and endothelial tube formation." (PMID 39315734, 2024).
renal cell carcinoma (4 papers, 2016 to 2025). "Furthermore, a study reported adrenomedullin promotes resistance to sunitinib, through the reduction of FDX1 expression levels, thus inhibiting cuproptosis in renal cell carcinoma." (PMID 40547013, 2025). "Additionally, adrenomedullin could reduce FDX1 transcription and suppress cuproptosis in renal cell carcinoma (RCC) through promoting p38/MAPK signaling pathway-mediated phosphorylation and nuclear translocation of Forkhead box O3 (FOXO3)." (PMID 38918694, 2024).
cardiac hypertrophy (3 papers, 2018 to 2023). "Furthermore, signaling pathways associated with adrenomedullin, dilated cardiomyopathy, cardiac hypertrophy, actin nucleation and cytoskeleton, cardiac remodeling and inflammation, and ERK/MAPK were among the top activated pathways." (PMID 36928240, 2023). "Increased cardiac hypertrophy and fibrosis were observed after subjecting heterozygous ADM knockout mice to stress-induced cardiac hypertrophy compared with their wild-type counterparts." (PMID 29520277, 2018).
Cerebral ischemia (3 papers, 2015 to 2023). Restriction of arterial blood supply to the brain associated with insufficient oxygenation to support the metabolic requirements of the tissue. "Adrenomedullin is a neuroprotective peptide, secreted widely in the central nervous system after cerebral ischemia as a response to hypoxia." (PMID 37508918, 2023). "Moreover, adrenomedullin provides neuroprotection against cerebral ischemia-induced injury while enhancing astrocyte migration." (PMID 26481857, 2015).
cervical cancer (3 papers, 2013 to 2019). A primary or metastatic malignant neoplasm involving the cervix. "In cervical cancer, miR-126 inhibits angiogenesis, microvessel density, and tumor growth by targeting expression of the pro-angiogenic gene adrenomedullin (ADM)." (PMID 31757094, 2019). "In cervical cancer, the repression of miR-126 may facilitate tumor angiogenesis and invasion growth by upregulating a proangiogenic gene adrenomedullin." (PMID 24350576, 2013). "This study suggests a cancer-stroma cross-talk that induces repression of miR-126 and upregulation of the pro-angiogenic gene adrenomedullin (ADM), and probably also other pro-angiogenic factors, to facilitate angiogenesis and invasive growth of cervical cancer." (PMID 27213336, 2016).
chronic pancreatitis (3 papers, 2021 to 2023). A chronic inflammatory process causing damage and fibrosis of the pancreatic parenchyma. "Patients with PC have been found to have higher serum levels of adrenomedullin, and the ADM gene encodes a peptide hormone that differs between individuals with chronic pancreatitis and healthy ones." (PMID 37941546, 2023). "In this manuscript, we describe that ductal cells and possibly subsets of ADM can express CD73 in the context of caerulein‐mediated acute or chronic pancreatitis." (PMID 36468677, 2023). "The serum level of adrenomedullin, a peptide hormone encoded by the ADM gene, was significantly increased in patients with PDAC compared to chronic pancreatitis and healthy individuals." (PMID 35002712, 2021).
colon cancer (3 papers, 2015 to 2020). "HIF-induced JMJD1A expression at 0.5% oxygen caused increased histone demethylation leading to the induction of the adrenomedullin (ADM) and growth and differentiation factor 15 (GDF15) genes, which promote tumor growth in renal and colon cancer cell lines." (PMID 26426056, 2015). "To investigate the contribution of adrenomedullin (AM) and its gene-related peptide, proadrenomedullin N-terminal 20 peptide (PAMP), to the progression and potential treatment of colon cancer we studied the effects of four small molecules (SM) related to AM and PAMP on a mouse model of colon cancer." (PMID 29235493, 2017).
diabetic retinopathy (3 papers, 2012 to 2020). "The data suggest that ADM may be involved in the pathogenesis of diabetic retinopathy, especially that retinal arteries have been recognized as its uptake point." (PMID 24347823, 2013). "It will also be important to determine whether there are changes in ADM expression or in the activity of its downstream signaling components in pathologies known to increase ADM levels such as diabetic retinopathy, glaucoma, retinitis pigmentosa, or uveitis." (PMID 22690112, 2012). "Since ADM is increased in eyes with ocular pathologies such as diabetic retinopathy, glaucoma, retinitis pigmentosa, and uveitis, the ADM signaling pathway may provide a new target for ameliorating these retinal pathologies." (PMID 22690112, 2012).
endotoxemia (3 papers, 2007 to 2013). "Furthermore, during rodent and human endotoxemia, hemodynamic stabilization with activated protein C was associated with lower blood NO and ADM levels." (PMID 26266790, 2013). "Plasma levels of endothelin-1 (ET-1) and adrenomedullin (ADM), two opposingly acting peptides, correlate with mortality in endotoxemia, but their measurement is cumbersome." (PMID 18080871, 2007). "Vasorelaxation might in this case rely on activation of constitutively expressed NO-synthases and/or on induction of adrenomedullin, a potent vasodilator, whose expression has been shown to be up-regulated in endotoxemia, the release of the vasodilator kynurenine or on COX2-derived thromboxane." (PMID 22970242, 2012).
lymph node metastasis (3 papers, 2003 to 2025). "We also found axillary lymph node metastasis to be significantly correlated with increased ADM plasma levels." (PMID 14612905, 2003). "Plasma ADM levels are elevated in patients with lymph node involvement and may represent an independent predictor of lymph node metastasis." (PMID 14612905, 2003). "Plasma ADM might represent an independent predictor of lymph node metastasis." (PMID 14612905, 2003).
Pleural effusion (3 papers, 2012 to 2024). The presence of an excessive amount of fluid in the pleural cavity. "Specifically, the presence of pleural effusion was associated with higher levels of pro-ADM (2.9440 vs. 1.1373 nmol/L, p < 0.001)." (PMID 22818355, 2012). "Additionally, increased ADM concentrations correlate with low albumin levels and greater pleural effusion, reflecting its association with organ dysfunction." (PMID 39458091, 2024). "Increased ADM values have also been correlated with low albumin levels and increased pleural effusion." (PMID 39458091, 2024). "Patients presenting complications had significantly higher levels of pro-ADM, especially as regards pleural effusion, bacterial pneumonia, empyema, and the need for interventional procedures." (PMID 36010070, 2022).
prostate carcinoma (3 papers, 2022 to 2025). A carcinoma that arises from epithelial cells of the prostate gland. "In prostate cancer patients, cancer cells secrete sEVs containing adrenomedullin which upregulates fatty acid oxidation via ERK1/2 and p38 MAPK axis contributing to the early weight loss associated with prostate cancer patients." (PMID 41322698, 2025).
pulmonary fibrosis (3 papers, 2011 to 2026). Chronic progressive interstitial lung disorder characterized by the replacement of the lung tissue by connective tissue, leading to progressive dyspnea, respiratory failure, or right heart failure. "RAMP2 overexpression in myofibroblasts was reported to enhance survival and reduce pulmonary fibrosis in the bleomycin mouse model by sensitizing adrenomedullin signaling." (PMID 32244228, 2020).
triple-negative breast carcinoma (3 papers, 2024 to 2025). An invasive breast carcinoma which is negative for expression of estrogen receptor (ER), progesterone receptor (PR), and human epidermal growth factor receptor 2 (HER2). "ADM, also referred to as adrenomedullin, is a bioactive peptide that has been associated with a poor prognosis in triple-negative breast cancer patients." (PMID 41150812, 2025). "In particular, the authors demonstrated how low levels of ADM in triple-negative breast cancer are associated with an overall poor prognosis." (PMID 39200990, 2024).
acute coronary syndrome (2 papers, 2017 to 2022). Signs and symptoms related to acute ischemia of the myocardium secondary to coronary artery disease. "Adrenomedullin (ADM) has been shown as prognosticator in CS after an acute coronary syndrome." (PMID 28050899, 2017). "As far as ADM is known, that increases in CAD and acute coronary syndromes, the relationship between the stage of CAD and proADM plasma levels has not been studied yet." (PMID 35522058, 2022).
Arthritis (2 papers, 2008 to 2010). Inflammation of a joint. "Daily injections of adrenomedullin into the knee joint spaces of rabbits with antigen-induced arthritis decreased joint swelling." (PMID 19014513, 2008). "Following the induction of arthritis in both knee joints by ovalbumin injection into the joint spaces of pre-immunized rabbits, increasing daily doses of adrenomedullin were injected into the knee joint spaces or saline was injected into the contralateral knee joint spaces as the control." (PMID 19014513, 2008). "In psoriasis, CCL4, GZMK and KLRF1 show significantly higher, while ADM, ANXA3, IL4, MMP9 and OLR1 show significantly lower expression levels in patients with arthritis negative psoriasis compared to patients with symptoms of arthritis." (PMID 20444268, 2010).
bacteremia (2 papers, 2018 to 2021). "NLCR, CRP, procalcitonin, neopterin and pro-ADM levels were insignificant in diagnosis of bacteremia in critically ill patients." (PMID 30559815, 2018). "In our study, NLCR, neopterin, pro-ADM and the other infection markers was investigated in septic patients as predictors of bacteremia." (PMID 30559815, 2018). "As a result, NLCR, CRP, procalcitonin, neopterin and pro-ADM levels were insignificant in diagnosis of bacteremia." (PMID 30559815, 2018). "NLCR, neopterin and pro-ADM levels were insignificant in predicting bacteremia (p>0.05)." (PMID 30559815, 2018). "Nevertheless, another study of critically ill cancer patient revealed that pro-ADM and PCT had similar areas under the roc curve for identifying bacteremia, both being superior to that of CRP." (PMID 33869250, 2021).
brain tumor (2 papers, 2024). "Furthermore, ADM mRNA expression levels in brain tumors are positively correlated with tumor grade." (PMID 38332637, 2024).